NDRG1 (N-myc downstream regulated 1)
Diseases named in the same sentence as NDRG1 in open-access papers (continued):
Sharing a sentence is not in itself a finding about the gene and the disease.
glioma (24 papers, 2013 to 2025). A benign or malignant brain and spinal cord tumor that arises from glial cells (astrocytes, oligodendrocytes, ependymal cells). "Simultaneously, a retrospective RNA-seq data analysis revealed that NDRG1 mRNA is an independent risk factor for overall survival (OS) in patients with glioma." (PMID 40332138, 2025). "NDRG1 is an independent risk factor for overall survival (OS) in glioma patients, and plays an important role in promoting VM in glioma patients." (PMID 39668822, 2024). "In untreated glioma patients, high NDRG1 expression was associated with increased survival, and the gene also reduced the rate of angiogenesis." (PMID 33300633, 2021). "The association between NDRG1 expression and glioma cell invasion was detected using a Matrigel invasion assay." (PMID 25777142, 2015). "N-myc downstream regulated gene 1 (NDRG1) has been implicated in many cellular processes including cell cycle progression, apoptosis, differentiation, and vesicular transport; it is downregulated in primary and metastatic cancers, including glioma." (PMID 32023813, 2020). "However, the mechanisms underlying the effects of NDRG1 on glioma tumorigenesis had yet to be elucidated." (PMID 25777142, 2015). "The pharmacological inhibition of SGK1 using the compound, EMD638683, prevented the NDRG1-mediated protection of glioma from TMZ." (PMID 40378957, 2025). "In this study, NDRG1 knockdown in human glioma cell lines resulted in sensitization to TMZ, and NDRG1 overexpression decreased TMZ-induced G2/M arrest." (PMID 40378957, 2025). "Of note, it was discovered via biomolecular fluorescence complementation assays that NDRG1 and MGMT directly associate in glioma cells." (PMID 40378957, 2025). "In order to explore the prognostic value of NDRG1 in glioma patients, we conducted Kaplan-Meier and Cox proportional hazards model analyses based on TCGA and CGGA databases." (PMID 39668822, 2024). "NDRG1, a hypoxia-inducible protein, is identified as a tumor suppressor in gliomas and glioblastomas." (PMID 36712870, 2022). "The expression of NDRG1 and Myc was investigated in 168 cases of glioma, and the expression was compared with the WHO grade and survival rate of the patients." (PMID 35448004, 2022). "The present review summarized that NDRG1 plays a critical role in progression, differentiation, and invasion in glioma and GBM, through its interaction with various key molecules and signaling pathways." (PMID 35448004, 2022). "In experiments with glioma cell lines, when NDRG1 overexpression was enforced using retroviral constructs expressing NDRG1, the percentage of apoptotic glioma cells increased relatively higher than in untransfected cells." (PMID 35448004, 2022). "Meanwhile, a study showed that high-grade glioma had the higher expression of NDRG1 mRNA and protein compared with grade II glioma." (PMID 35448004, 2022). "The anti‐angiogenesis gene TNFSF15 showed a 30‐fold increase in glioma development, with an increasing expression of NDRG1, and demonstrated that anti‐angiogenesis was positively correlated with TNFSF15." (PMID 33300633, 2021). "N‐myc downstream‐regulated gene‐1 (NDRG1) is considered a regulatory gene in the hypoxic microenvironment of glioma." (PMID 33300633, 2021). "In a recent work, the authors showed that GOLPH3 knockdown in U251 promotes glioma cell apoptosis and increases cellular levels of both NDRG1 and cleaved caspase 3 by ~55% and ~80%, respectively." (PMID 32023813, 2020). "A larger study investigating different glioma grades (n = 168) found reduced NDRG1 expression in gliomas, which was negatively correlated to glioma grade." (PMID 31485792, 2019). "Cell line experiments in glioma cells showed that NDRG1 inhibits cell proliferation and invasion and induced apoptosis." (PMID 31485792, 2019).
glioma (continued). "The NDRG1 expression pattern was investigated in tissue sections of grade II glioma (n = 40) where moderate-to-high NDRG1 protein expression was found as a prognostic factor for reduced risk of glioma progression and progression-free survival." (PMID 31485792, 2019). "Here, we found NDRG1 upregulated in VEGFR-2-positive glioma cells, which explains well the increased chemoresistance to TMZ (and not to radiotherapy) observed in these cells." (PMID 25682871, 2015). "NDRG1 protein expression levels were low in the U87 MG and SHG-44 glioma cells, whereas high expression levels of NDRG1 were observed in the normal astroglial cell line (1800), as determined by western blotting." (PMID 25777142, 2015). "Mice injected with glioma cells over-expressing NDRG1 exhibited significantly smaller tumors as compared with those in the control group (P<0.005)." (PMID 25777142, 2015). "The present study examined the expression levels of NDRG1 in the established human glioma cell lines U87 MG and SHG-44, and in the normal astroglial cell line 1800." (PMID 25777142, 2015). "The present study used the U87 MG and SHG-44 human glioma cell lines as well as the normal human astrocyte cell line 1800, which are known to have differential NDRG1 expression." (PMID 25777142, 2015). "N-myc downstream-regulated gene 1 (NDRG1) was previously shown to exhibit low expression in glioma tissue as compared with that in normal brain tissue; however, the role of NDRG1 in human glioma cells has remained to be elucidated." (PMID 25777142, 2015). "In order to elucidate the role of NDRG1 in glioma, RV-NDRG1 was transiently transfected into U87 MG glioma cells." (PMID 25777142, 2015). "The present study further examined the effects of NDRG1 on glioma growth by establishing a U87 MG xenograft nude mouse glioma model." (PMID 25777142, 2015). "Overall, these results suggest that gliomas with higher malignancy levels are enriched with NDRG1." (PMID 39668822, 2024). "Besides, MORC2 is up-regulated in glioma cells and binds to the NDRG1 promoter to promote glioma cell growth and metastasis by regulating PTEN/PI3K/AKT signaling." (PMID 37692502, 2024). "In addition, up-regulated MORC2 promotes glioma cell growth by suppressing the NDRG1 promoter activity and regulating PTEN/PI3K/AKT signaling." (PMID 37692502, 2024). "NDRG1 expression of mRNA and protein was decreased in gliomas compared with a normal brain." (PMID 35448004, 2022). "The function of NDRG1 in gliomas may be affected by the balance with other NDRG family genes and requires further study." (PMID 35448004, 2022). "Furthermore, experiments using human glioma cell lines found NDRG1 overexpression inhibits cell proliferation and invasion and suppresses tumorigenesis in the subcutaneous tumor mouse model." (PMID 35448004, 2022). "In addition, NDRG1 is affected by not only the tumor microenvironment but also glioma treatments such as radiation, chemotherapeutic agents, and steroids, and its pathway is the mechanistic target of the rapamycin C2 (mTORC2)/SGK1 pathway." (PMID 35448004, 2022). "From these findings, NDRG1 has been considered a potent tumor suppressor in gliomas." (PMID 35448004, 2022). "Furthermore, when the target was limited to grade II glioma, post-surgically untreated grade II gliomas showed that moderate-to-high expression of the NDRG1 protein was correlated with growth delay and improved progression-free survival, but not OS." (PMID 35448004, 2022). "GOLPH3 knockdown increases NDRG1 and triggers apoptosis in glioma cells." (PMID 33015040, 2020). "Furthermore, supernatant of U87MG glioma NDRG1 knockdown contained proangiogenic proteins that increased sprouting in HUVEC cells." (PMID 32094357, 2020). "Further, NDRG1 over-expressing malignant glioma cells exhibit reduced angiogenic activity." (PMID 32094357, 2020).
glioma (continued). "Additionally, tumorigenicity of subcutaneously injected NDRG1-overexpressing glioma cells was reduced in vivo, concluding that NDRG1 likely has a tumor-suppressive function in glioma." (PMID 31485792, 2019). "Activation of mTORC2 and thus SGK1-phosphorylated NDRG1 is increased in temozolomide resistant glioma cell lines and NDRG1 expression is elevated in tissues specimens from glioma patients, suggesting that this is mechanistically important for MGMT-conferred resistance to alkylating therapeutics." (PMID 29301334, 2018). "To conclude, the inhibition of p-NDRG1 by DHA as well as DHA-induced ROS represent two possible mechansims how DHA might overcome therapy-induced resistance in gliomas." (PMID 27447560, 2016). "Therefore, it is required to study the role of NDRG1 in the regulation of glioma cell growth, survival and invasion." (PMID 25777142, 2015). "Further evidence regarding this finding was obtained from glioma cells with NDRG1 knockdown." (PMID 25777142, 2015). "Though otherwise robustly induced with hypoxia in perinecrotic tumor areas of glioblastoma, NDRG1 was found here to be activated in VEGFR-2-positive glioma cells, i.e., in cells that chiefly reside within the tumor infiltration zone where sufficient oxygen supplies are presumably given." (PMID 25682871, 2015). "The present study aimed to determine whether NDRG1 could inhibit proliferation and invasion of glioma through the PI3K/Akt signaling pathway." (PMID 25777142, 2015). "mRNA and protein expression of NDRG1 was found to be decreased in primary cancer and metastatic cells, including colon, prostate, breast and esophageal squamous cancer, as well as glioma, as compared with that in normal cells." (PMID 25777142, 2015). "In conclusion, the present study demonstrated that NDRG1 is lowly expressed in glioma cells." (PMID 25777142, 2015). "The present study demonstrated that NDRG1 is important in gliomas." (PMID 25777142, 2015). "The present study aimed to determine the expression and pathological roles of NDRG1 in human glioma, and to investigate whether NDRG1 could serve as a potential target for the treatment of glioma." (PMID 25777142, 2015). "Furthermore, a subcutaneous tumor mouse model was used to investigate the effects of NDRG1 on the growth of glioma cells in vivo." (PMID 25777142, 2015). "The transcriptional repression of human NDRG1 by Myc may be involved in glioma progression." (PMID 35448004, 2022). "Additionally, a large study in 168 patients with glioma with different WHO grade identified that decreased NDRG1 expression was negatively correlated with WHO grade; moreover, low expression of NDRG1 was associated with significantly lower OS, independent of any prognostic factors." (PMID 35448004, 2022). "Collectively, although these investigations showed that NDRG1 might be suggested to have the potential of a tumor suppressor gene in glioma, several factors might lead to poor prognosis and reduced OS, such as tumor environment (e.g., hypoxia, stress condition) and genotoxic changes by chemotherapy." (PMID 35448004, 2022). "However, the role of NDRG1 in human glioma has yet to be fully elucidated." (PMID 25777142, 2015). "However, it remains to be elucidated why NDRG1 has a low level of expression in glioma." (PMID 25777142, 2015). "The findings of the present study indicated that NDRG1 is required for the inhibition of gliomagenesis; therefore, targeting NDRG1 and its downstream targets may represent novel therapies for the treatment of glioma." (PMID 25777142, 2015). "In addition, the results demonstrated that NDRG1 may have an important role in the regulation of growth and invasion of glioma cells." (PMID 25777142, 2015). "It was also demonstrated that dexamethasone (DEX), a steroid administered as standard of care in glioma treatment, induced SGK1 transcription resulting in increased phosphorylation of NDRG1 at T346." (PMID 40378957, 2025).
glioma (continued). "NDRG1 showed a strong correlation with EMT and VM in the CGGA and TCGA databases, which lead to glioma growth and invasion." (PMID 39668822, 2024). "In this review, we examine the literature on NDRG1 in the area of gliomas including GBM cells and GSCs and suggest the potential of novel therapies focusing on NDRG1 for GBM." (PMID 35448004, 2022). "Both mRNA and protein expression of Myc were higher in gliomas, and the expression increased from WHO grade I to WHO grade IV, which was a reverse expression of NDRG1." (PMID 35448004, 2022). "The study of the microrchidia family CW-type zinc finger 2 (MORC2), which was a chromatin modifier, reported that MORC2 binding to the NDRG1 promotor inactivated PTEN/PI3K/AKT signaling and promoted the growth of glioma cells." (PMID 35448004, 2022). "Small interfering (si)RNA targeting NDRG1, and NDRG1 overexpression vectors were transfected into the SHG-44 and U87 MG glioma cells, respectively." (PMID 25777142, 2015). "Overexpression of NDRG1 was shown to inhibit cell proliferation and invasion, and induce apoptosis in the U87 MG glioma cells, whereas NDRG1 downregulation increased proliferation, suppressed apoptosis and promoted invasion of the SHG-44 glioma cells." (PMID 25777142, 2015). "In the CGGA database, NDRG1 is highly enriched in high-grade gliomas and IDH-wildtype gliomas." (PMID 39668822, 2024). "Furthermore, in the NDRG family, NDRG2 acts in a tumor-suppressive manner similar to NDRG1, while NDRG4 is lowly expressed in gliomas and is considered as a poor prognostic factor." (PMID 35448004, 2022). "Moreover, NDRG1, NDRG2, and NDRG4 are all involved in cancers of the nervous system, such as glioma, neuroblastoma, or meningioma." (PMID 31485792, 2019). "As DHA is an approved drug which additionally suppresses TMZ–induced activation of phospho-NDRG1, a known mechanism of resistance, our data builds on previous results to warrant initiating clinical trials combining TMZ with DHA in the treatment of glioma patients." (PMID 27447560, 2016). "This later pharmacological effect was not specific for glioma, as EMD638683 also decreased NDRG1 levels in pancreatic, breast, colon, and ovarian cancer cells." (PMID 40378957, 2025). "However, there is a negative correlation between tumor suppressor gene NDRG1 expression and GOLPH3 expression in glioma samples." (PMID 33015040, 2020). "On the other hand, NDRG1 knockdown does not affect GOLPH3 expression but lowers the level of cleaved caspase 3, suggesting that GOLPH3 increases the cleavage of caspase 3 and apoptosis of glioma cells partially via downregulating NDRG1." (PMID 32023813, 2020).
bladder cancer (18 papers, 2013 to 2025). "N-myc downstream regulated 1 (NDRG1), a protein commonly upregulated in various cancers, including bladder cancer, is implicated in stress responses, cell growth, and differentiation." (PMID 38339062, 2024). "Considering that urine is the ideal body fluid to test for bladder cancer, we determined whether NDRG1 could be detected in patients’ urine by enzyme-linked immunosorbent assay (ELISA)." (PMID 30914736, 2019). "In conclusion, to our knowledge, our study provided the first evidence that high expression of NDRG1 in bladder cancer patients is associated with advanced tumour stage and poor outcomes and could be a diagnostic and prognostic biomarker." (PMID 30914736, 2019). "For example, in DNA damage contexts, NDRG1 was shown to translocate to the nucleus in bladder carcinoma cells, while hypoxic conditions in trophoblasts enhanced NDRG1 expression in the nucleus and cytoplasm." (PMID 36497221, 2022). "Taken together, our results indicated that TGFβ downregulated GDF15 expression via Smad pathways to block its downstream genes, maspin and NDRG1, in bladder carcinoma cells." (PMID 35884930, 2022). "Taken together, CAPE treatment upregulating GDF15 secretion in vitro and in vivo induced the gene expressions of NDRG1 and maspin in bladder carcinoma cells." (PMID 34662721, 2022). "This study aimed to determine the antitumor effect of CAPE and evaluate the potential molecular mechanisms of CAPE on the expression of GDF15 and its downstream genes, NDRG1 and maspin, in human bladder carcinoma cells." (PMID 34662721, 2022). "Previously, we reported that GDF15 enhanced the expressions of N-myc downstream-regulated gene 1 (NDRG1) and maspin to downregulate the cell proliferation and invasion in bladder carcinoma cells." (PMID 34662721, 2022). "In the present study, our results showed that GDF15 and its downstream genes, maspin and NDRG1 were downregulated by TGFβ through the Smad 2/3 and Smad 1/5 activation in bladder carcinoma cells." (PMID 35884930, 2022). "CAPE-induced expressions of NDRG1 and maspin decreased cell proliferation and invasion of bladder carcinoma cells in a GDF15-dependent manner in vitro." (PMID 34662721, 2022). "To investigate the efficacy of NDRG1 as a prognostic biomarker, we further studied the correlation between NDRG1 expression and bladder cancer patient outcomes." (PMID 30914736, 2019). "The area under the curve (AUC) of NDRG1 expression to diagnose bladder cancer was 0.909 (95% CI, 0.829–0.989), with a sensitivity of 84.6% and a specificity of 86.7%." (PMID 30914736, 2019). "NDRG1 protein levels were significantly increased in bladder cancer patients and correlated with tumour stage (p = 0.025), lymph node metastasis (p = 0.034) and overall survival (p = 0.016)." (PMID 30914736, 2019). "Our study enrolled 100 bladder cancer patients to detect NDRG1 expression in tumour tissues by immunohistochemistry." (PMID 30914736, 2019). "To identify the expression of NDRG1 in human tissues, we first obtained 15 pairs of tumour and corresponding tumour-free samples from bladder cancer patients for analysis." (PMID 30914736, 2019). "We demonstrated here for the first time that the NDRG1 mRNA and protein expression levels are significantly upregulated in bladder cancer tissues." (PMID 30914736, 2019). "Next, the receiver operating characteristic (ROC) curve based on the ELISA results was plotted to evaluate the potential of urinary NDRG1 as a non-invasive biomarker for the diagnosis of bladder cancer." (PMID 30914736, 2019). "The experiments indicated that MT3 is an arsenic- and hypoxia-upregulated oncogene that promotes cell growth and invasion of bladder carcinoma cells via downregulation of NDRG1, NDRG2, and MASPIN expressions." (PMID 30813460, 2019).